INSIG2 (insulin induced gene 2)
Description:
Oxysterol-binding protein that mediates feedback control of cholesterol synthesis by controlling both endoplasmic reticulum to Golgi transport of SCAP and degradation of HMGCR. Acts as a negative regulator of cholesterol biosynthesis by mediating the retention of the SCAP-SREBP complex in the endoplasmic reticulum, thereby blocking the processing of sterol regulatory element-binding proteins (SREBPs) SREBF1/SREBP1 and SREBF2/SREBP2. Binds oxysterol, including 22-hydroxycholesterol, 24-hydroxycholesterol, 25-hydroxycholesterol and 27-hydroxycholesterol, regulating interaction with SCAP and retention of the SCAP-SREBP complex in the endoplasmic reticulum. In presence of oxysterol, interacts with SCAP, retaining the SCAP-SREBP complex in the endoplasmic reticulum, thereby preventing SCAP from escorting SREBF1/SREBP1 and SREBF2/SREBP2 to the Golgi. Sterol deprivation or phosphorylation by PCK1 reduce oxysterol-binding, disrupting the interaction between INSIG2 and SCAP, thereby promoting Golgi transport of the SCAP-SREBP complex, followed by processing and nuclear translocation of SREBF1/SREBP1 and SREBF2/SREBP2. Also regulates cholesterol synthesis by regulating degradation of HMGCR: initiates the sterol-mediated ubiquitin-mediated endoplasmic reticulum-associated degradation (ERAD) of HMGCR via recruitment of the reductase to the ubiquitin ligase RNF139.
Synonyms: INSIG-2
Tractability: Small molecule: a structure with a bound ligand is known. Antibody: UniProt predicts a signal peptide or a membrane-spanning region. PROTAC: UniProt records ubiquitination sites on it; ubiquitination databases record sites on it.
Gene: Protein-coding gene on chromosome 2 (118,088,137 to 118,112,313, forward strand). Ensembl gene ENSG00000125629.
Subcellular location: Endoplasmic reticulum membrane
Pathways (Reactome):
Metabolism: Regulation of cholesterol biosynthesis by SREBP (SREBF)
Gene Ontology:
Molecular function: oxysterol binding; protein binding; protein sequestering activity
Biological process: cholesterol biosynthetic process; SREBP signaling pathway; SREBP-SCAP complex retention in endoplasmic reticulum; cellular response to insulin stimulus; cholesterol metabolic process; regulation of transcription by RNA polymerase II; response to fatty acid; response to insulin; response to lipid
Cellular component: endoplasmic reticulum; endoplasmic reticulum membrane; SREBP-SCAP-Insig complex
Genetic constraint (gnomAD): Loss-of-function variants: 7 observed, 21 expected, observed/expected ratio (o/e) 0.33, 90% interval 0.19 to 0.63. The upper end of that interval is the gene's LOEUF score, 0.63, which puts it in group 2 of 6, group 1 being the genes least tolerant of losing a copy. Missense variants: 154 observed, 243.86 expected, observed/expected ratio (o/e) 0.63, 90% interval 0.55 to 0.72. Synonymous variants: 83 observed, 88.9 expected, observed/expected ratio (o/e) 0.93, 90% interval 0.78 to 1.12.
Homologues: Orthologues: chimpanzee INSIG2 (100% identical), rabbit INSIG2 (100% identical), macaque INSIG2 (99% identical), pig INSIG2 (99% identical), mouse Insig2 (97% identical), rat Insig2 (96% identical), dog INSIG2 (93% identical), zebrafish insig2 (80% identical), tropical clawed frog insig2 (77% identical). Paralogues in human: INSIG1 (72% identical).
Diseases named in the same sentence as INSIG2 in open-access papers:
INSIG2 is named in the same sentence as 36 diseases in open-access papers, as found by Europe PMC text mining. Sharing a sentence is not in itself a finding about the gene and the disease. The quoted sentences say what the papers report.
Obesity (45 papers, 2006 to 2025). Accumulation of substantial excess body fat. "The completion of the human genome project led to the discovery of the first locus, to be associated with obesity was insulin-induced gene 2 (INSIG2)." (PMID 40108925, 2025). "The association of the rs7566605 SNP of INSIG2 with predisposition to obesity is controversial, with data supporting this correlation in adults with severe obesity." (PMID 36986146, 2023). "Genetic variants in INSIG2 (rs75666605) have been associated with severe obesity in a North Indian human population and increased blood pressure and triglyceride levels in Brazilian obese patients." (PMID 35945490, 2022). "The single nuclear polymorphism (SNP) rs7566605 of INSIG2 is associated with INSIG2 dysregulation and a 40% increased risk of developing obesity." (PMID 36012526, 2022). "This is the first study of the association between the SREBF2 gene and INSIG2 polymorphisms and obesity and dyslipidemia in Thai psychotic disorder patients treated with risperidone." (PMID 34683084, 2021). "In conclusion, this is the first study of the relationship between the SREBF2 gene and INSIG2 polymorphisms and obesity and dyslipidemia in Thai psychotic disorder patients treated with risperidone." (PMID 34683084, 2021). "Many studies have revealed a significant association between obesity or BMI and the INSIG2 (rs7566605) polymorphism." (PMID 34683084, 2021). "There is an interesting SNP; rs7566605, which is located 10 kb upstream of INSIG-2, was found to be associated with obesity, assessed by BMI." (PMID 32596317, 2020). "The aim of this study was to examine the association of INSIG2 (rs7566605) gene polymorphism with obesity and obesity associated phenotypes in North Indian subjects." (PMID 28160769, 2017). "A significant association was observed for INSIG2 (rs7566605) single nucleotide polymorphism with obesity and obesity-related phenotypes." (PMID 28160769, 2017). "The present study observed significant association between INSIG2 (rs7566605) single nucleotide polymorphism and obesity, as well as obesity-associated phenotypes in North Indian population." (PMID 28160769, 2017). "Apart from common DIS regulated genes the transcription factors FOXO1 and FOXA2 and the insulin induced gene 2 are specific targets of miR-335-5p; note polymorphisms of INSIG2 are associated with severe obesity." (PMID 27045805, 2016). "Several studies have shown a significant association between INSIG2 variant rs7566605 and obesity or BMI." (PMID 25607990, 2015). "In conclusion, the study identified a gender-specific effect of INSIG2 -102G>A polymorphism on risk of severe obesity and waist circumference in Chinese boys." (PMID 26161092, 2015). "It was previously reported that the effects of some obesity-related gene variants have gender-specific effects, including a male-specific effect of the near-INSIG2 variant (rs7566605, upstream -102G>A) on waist-hip ratio in Norway adolescents and adults." (PMID 26161092, 2015). "This study aimed to investigate the association of INSIG2 gene -102G>A polymorphism with obesity related phenotypes in Chinese children and test gender-specific effects." (PMID 26161092, 2015). "A polymorphism of SNP rs7566605 near insulin-induced gene 2 (INSIG2) has been identified as a strong candidate gene for obesity, through its feedback control of lipid synthesis." (PMID 25607990, 2015). "rs7566605, which is located 10 kb upstream of INSIG2, was reported to have the strongest association with obesity among 86 604 SNPs." (PMID 24959828, 2014). "All risk alleles significantly associated with obesity were consistent with those previously reported, except for INSIG2 rs7566605 as the risk allele is “C” in Europeans and “G” in the Mexican population." (PMID 23950976, 2013). "FTO, TMEM18 and INSIG2 variants showed the most significant associations with obesity in this population." (PMID 23950976, 2013).
Obesity (continued). "The INSIG2 heterozygous "GC" genotype was present at 43.6% and the INSIG2 low obesity risk "GG" was present in 46.5%." (PMID 20920244, 2010). "Association with increased risk of obesity has also been demonstrated for SNP rs7566605 located ~10 kb upstream of the insulin-induced gene-2 (INSIG2), which was detected in the first population-based GWAS for body weight." (PMID 20092643, 2010). "The adjusted odds ratio for a history of PVD in older men who carried at least one INSIG2 obesity/lipid allele increased to 3.4 (p = 0.013)." (PMID 20920244, 2010). "The INSIG2 gene has been implicated in cholesterol metabolism and a single nucleotide polymorphism (SNP) near INSIG2 has been shown to be associated with obesity." (PMID 20920244, 2010). "A polymorphism of the INSIG2 gene was identified as being associated with obesity in one of the first genome-wide association studies." (PMID 19851442, 2009). "In a genome-wide association study performed in the Framingham Offspring Cohort, individuals homozygous for the rs7566605 C allele located upstream of insulin-induced gene 2 (INSIG2) were reported to incur an increased risk of obesity." (PMID 19523229, 2009). "INSIG2, showing involvement with cholesterol metabolism in studies using the cell line and mice, has been identified as an obesity-susceptible gene in a recent whole-genome association study." (PMID 19772594, 2009). "There are a variety of possible reasons to explain the different associations detected between the INSIG2 variant and obesity in different populations." (PMID 19523229, 2009). "A genome wide association study found significant association of a sequence variant, rs7566605, in the insulin-induced gene 2 (INSIG2) with obesity." (PMID 20028541, 2009). "For all of the obesity-related continuous traits, the power reached 95% to observe a small effect of the INSIG2 sequence variant (R2 ≤ 1%) given the INSIG2 rs7566605 minor allele frequencies found for each study population after stratification by race." (PMID 19523229, 2009). "INSIG2 was also independently identified as a genetic determinant of obesity in a genome-wide association study carried out in 1,000 unrelated Caucasian adults of Northern European origin." (PMID 19523229, 2009). "One of the first genome-wide association (GWA) studies ever and the first on obesity identified the INSIG2 gene represented by the rs7566605 polymorphism as a novel gene for common obesity." (PMID 19851442, 2009). "The INSIG2 rs7566605 polymorphism was identified for obesity (BMI≥30 kg/m2) in one of the first genome-wide association studies, but replications were inconsistent." (PMID 19851442, 2009). "This supports and extends the original finding that there is an association between measures of obesity and INSIG2 rs7566605 and further implicates this polymorphism in fat regulation." (PMID 19105843, 2008). "The rs7566605 located 10 kb upstream of the insulin induced gene 2 (INSIG2), was the first common obesity-related gene variant to be identified through a GWA approach, including 694 individuals." (PMID 18682847, 2008). "Our study also examined the rs7566605 genetic variant, located 10 kb upstream of the INSIG2 gene, which was recently shown in a multi-staged genome-wide association study to be associated with obesity." (PMID 18096054, 2007). "Another potential candidate for MetS is the rs7566605 genetic variant, located 10 kb upstream of the insulin-induced gene 2 (INSIG2) gene, which was shown in a multi-staged genome-wide association study to be associated with obesity." (PMID 18096054, 2007). "The rs7566605 marker, located near the INSIG2 gene, has been found to be associated with obesity, making it also a potential genetic determinant for MetS." (PMID 18096054, 2007). "A SNP upstream of the INSIG2 gene, rs7566605, was recently found to be associated with obesity as measured by body mass index (BMI) by Herbert and colleagues." (PMID 17465681, 2007).
Obesity (continued). "Furthermore, we observed a positive correlation between the reduction of glucose and proteins associated with alleviating obesity and type 2 diabetes, such as Insig2, Dgat2 and Rbp4." (PMID 38188177, 2024). "Interestingly, in a pediatric cohort, homozygosity for the obesity risk C allele was associated with higher glucose concentrations, possibly introducing an indirect role of INSIG2 in promoting adiposity, through its effect on glucose metabolism." (PMID 36986146, 2023). "Considering the prominent role of these genes in metabolic adverse effects, we hypothesized that the genetic SREBF2 gene and INSIG2 polymorphisms might be involved in the increased risk of obesity and dyslipidemia in Thai patients treated with risperidone." (PMID 34683084, 2021). "The objective of this study was to examine the association of the SREBF2 gene (rs1052717, rs2267439, and rs2267443) and INSIG2 (rs7566605, rs11123469, and rs17587100) polymorphisms on the presence of obesity and dyslipidemia in Thai psychotic disorder patients treated with risperidone." (PMID 34683084, 2021). "Since then, association studies between INSIG2 variations and obesity have been performed." (PMID 26161092, 2015). "For obesity is associated with lipid metabolism, INSIG2 may influence the development of obesity by regulating lipid synthesis." (PMID 26161092, 2015). "The association of -102G>A with severe obesity suggested that the proximal promoter region might impact the function of INSIG2 gene." (PMID 26161092, 2015). "Polymorphisms in INSIG2 may be important in the development of obesity through its effects on lipid regulation." (PMID 25607990, 2015). "Our finding of the association of -102G>A with severe obesity and waist circumference in boys provided evidence for gender disparity of the INSIG2 gene effects, which will be helpful for identifying genetic factors related to childhood obesity and developing early prevention strategy." (PMID 26161092, 2015). "Five common variants: rs17782313 and rs1770633 (melanocortin 4 receptor (MC4R); rs7566605 (insulin induced gene 2 (INSIG2); rs9939609 and rs1121980 (fat mass and obesity associated (FTO) were genotyped in 2 cohorts of Swedish women: PEAK-25 (age 25, n = 1061) and OPRA (age 75, n = 1044)." (PMID 24516669, 2014). "The INSIG2 gene has been reported to be associated with increased risk of obesity." (PMID 24516669, 2014). "SNP rs7566605 in INSIG2 gene is a common genetic variant associated with obesity." (PMID 22355322, 2012). "Age and gender may influence the association of the INSIG2 obesity SNP with PVD and cerebrovascular disease in patients with pre-existing CVD." (PMID 20920244, 2010). "Association of INSIG2 obesity allele and cardiovascular phenotypes by gender and age." (PMID 20920244, 2010). "The INSIG2 "C" SNP is considered the 'obesity/lipid risk' allele." (PMID 20920244, 2010). "Exploring potential sources of heterogeneity for the INSIG2 rs7566605 association with obesity (Hypotheses 3–5)." (PMID 19851442, 2009). "Main meta-analysis results of the INSIG2 rs7566605 association with obesity." (PMID 19851442, 2009). "An additional reason for the failure to replicate an association between the INSIG2 genetic variant and measures of obesity could be low statistical power." (PMID 19523229, 2009). "A common SNP upstream of the INSIG2 gene, rs7566605 (g.-10,1025G>C, Chr2:118,552,255, NT_022135.15), was reported to be associated with obesity (Body Mass Index, [BMI]) in a genome-wide association scan using the Framingham Heart Study but has not been reproduced in other cohorts." (PMID 19105843, 2008). "Moreover, an independent GWA scan, comprising 1,000 unrelated U.S. Caucasians, has observed an association between the INSIG2 rs7566605 variant and obesity." (PMID 18682847, 2008).
Obesity (continued). "We (I.M.H. and colleagues) are in the process of organizing a meta-analysis to reexamine the INSIG2 association in light of these hypotheses to better understand the relationship of this gene to obesity in the population." (PMID 17465681, 2007). "INSIG2 encodes a 225-aminoacid protein which blocks the proteolytic activation of sterol regulatory element-binding proteins, thus having antilipogenic effects, making it an attractive candidate for obesity-related traits." (PMID 18096054, 2007). "In addition, the administration of caffeine in mice resulted in decreased or increased levels of certain proteins, such as Insig2, Rbp4, and Igfbp1, which have been associated with improved obesity, type 2 diabetes mellitus (T2DM), and cardiovascular pathologies." (PMID 38188177, 2024). "Concerning INSIG2, since INSIG2 has been functionally linked to lipid metabolism, owing to its role in endogenous cholesterol and fatty acid synthesis feedback inhibition, INSIG2 might be a candidate gene for obesity and dyslipidemia." (PMID 34683084, 2021). "Thus, the association between rs7566605 in the INSIG2 gene and obesity remains controversial." (PMID 28160769, 2017). "The association of INSIG2 gene with obesity may change direction with age." (PMID 20354568, 2009). "The expression of diacylglycerol O-acyltransferase 2 (Dgat2), responsible for triacylglycerol synthesis, and insulin-induced gene 2 protein (Insig2), involved in cholesterol synthesis and obesity, were down-regulated in FL." (PMID 38188177, 2024). "Further studies are needed to assess the role of the SREBF2 gene and INSIG2 in obesity and dyslipidemia." (PMID 34683084, 2021). "The BDNF (rs925946), INSIG2 (rs3771942) and CNR1 (rs6454674) variants are well stablished genetic determinants of obesity." (PMID 34683180, 2021). "Data mapping of quantitative trait loci in mice for obesity and obesity-related traits and their response to high-fat diet have shown the linkage of the INSIG2 gene with fat depots and serum cholesterol levels." (PMID 28160769, 2017). "Among the INSIG-SCAP-SREBP pathway genes, INSIG2 has been the most frequently studied gene in obesity researches." (PMID 25028659, 2014). "We identified a 3-locus interaction on obesity in GMDR analyses (P = 0.001), involving 3 genetic variants of INSIG2, SCAP, and SREBP2." (PMID 25028659, 2014). "After adjusting for age, sex and admixture, significant associations with obesity were found for 6 genes in the case-control study (ADIPOQ, FTO, TMEM18, INSIG2, FAIM2/BCDIN3 and BDNF)." (PMID 23950976, 2013). "Other loci, including the INSIG2, TMEM18, KCTD15, SH2B1, MTCH2, GNPDA2, BDNF, or CHST8 genes, have also been associated with obesity." (PMID 24267414, 2013). "The three-way gene-gene interaction involves GSTP1 and INSIG2 characterize the obesity affects on antioxidative gene further influence asthma." (PMID 22355322, 2012). "The INSIG2 gene is a good candidate for being related to obesity because of its function in lipid metabolism, particularly in blocking the processing of SREBPs in response to cholesterol or insulin." (PMID 20955599, 2010). "Other GWA studies have reported variants in the proximity of INSIG2 and within PFKP as novel obesity gene loci, however, attempts to replicate the association for the INSIG2 variant have been inconsistent, which also appears true for variation in PFKP." (PMID 19245693, 2009). "INSIG2 is considered to be a candidate gene with respect to involvement in the development of obesity." (PMID 19772594, 2009). "The INSIG2 rs7566605 and PFKP rs6602024 polymorphisms have been identified as obesity gene variants in genome-wide association (GWA) studies." (PMID 18682847, 2008). "INSIG2 is the predominant protein isoform in adipocytes, and regulates the transcription of genes promoting fatty acid synthesis and adipogenesis, making INSIG2 a good biological candidate gene for obesity." (PMID 18682847, 2008).